SNAI1 (snail family transcriptional repressor 1)
Diseases named in the same sentence as SNAI1 in open-access papers (continued):
Sharing a sentence is not in itself a finding about the gene and the disease.
melanoma (continued). "The EMT transcription factor Snail/SNAI1, undetectable in primary human melanocytes, plays a role during the phenotypic transition leading to malignant melanomas, and its expression is considered a characteristic of the undifferentiated/mesenchymal state of melanoma." (PMID 38247872, 2024). "Notably, the previous proteome analysis of “normal” and “acidified” melanoma EVs revealed many differences in the expression of the prooncogenic proteins; however, the increased expression of SNAI1 and CD133 in “acidified” EVs was revealed here for the first time." (PMID 35327461, 2022). "The gain of invasive capability was also associated with an increased expression of EMT genes (e.g., CDH2, FN1, VIM, SNAI1), as revealed by both RT-qPCR and WB analyses of bulk tumors, Bdmc+/+ and Bdmc−/− cells and siAMBRA1 human melanoma SK-Mel-5, MeWo and SK-Mel-2 cells." (PMID 33953176, 2021). "Similarly, miR-153 could suppress cell proliferation and invasion by targeting snail family transcriptional repressor 1 (SNAI1) in melanoma." (PMID 31547242, 2019). "The area percentage of SNAI1-positive cells showed a significantly higher area percentage score in BRAF+ and BRAF− melanoma samples than in dysplastic nevus (p < 0.01) and melanoma in situ samples (p < 0.0001)." (PMID 39273022, 2024). "The survival rates in relation to the high and low mRNA expressions of LOXL3, NES, and SNAI1 in both BRAF-positive (BRAF+) and BRAF-negative (BRAF−) melanoma were analyzed." (PMID 39273022, 2024). "LOXL3, SNAI1, and NES are key factors in melanoma genesis, regulating tumor growth, metastasis, and cellular differentiation." (PMID 39273022, 2024). "EMT-TFs like SNAI1/2, ZEB1/2, and TWIST control the phenotype switching and are crucial for melanoma development." (PMID 38426087, 2024). "In our study, we explored the potential role of LOXL3, SNAI1, and NES in melanoma progression and metastasis among patients with dysplastic nevi, melanoma in situ, and BRAF+ and BRAF− metastatic melanoma, using immunofluorescence and qPCR analysis." (PMID 39273022, 2024). "Our study, using two experimental methods, immunofluorescence and qPCR analysis, reports on the aberrant LOXL3, SNAI1, and NES expression and their co-expression in dysplastic nevi, melanoma in situ, and BRAF+ and BRAF– melanoma." (PMID 39273022, 2024). "Quantitative cell evaluation of LOXL3, NES, and SNAI1 immunoreactivity in dysplastic nevi, melanoma in situ, and BRAF− and BRAF+ melanoma was performed by determining the section percentage area of the epidermal region." (PMID 39273022, 2024). "The major point of our interest was to explore the co-expression of LOXL3, SNAI1, and NES in melanoma development and their supposed role in EMT." (PMID 39273022, 2024). "The DepMap survey also found significant direct relationships between SNAI1 and ZEB1 as well as SNAI2 and ZEB2 in melanoma cell lines, further supporting a potential role for snail and ZEB transcription factors in the CoREST-mediated phenotype switch." (PMID 38300709, 2024). "Our analyses exposed a pro-metastatic program in melanoma where aberrantly expressed NR2F2-Iso2 regulates the transactivating capacity of NR2F2-Iso1 over differentiation (e.g., PMEL) and metastasis (e.g., SNAI1) - regulating gene sets." (PMID 37015919, 2023). "Acidification of metastatic melanoma environment made EVs more prooncogenic with increased expression of prooncogenic mi221 RNA, stemless factor CD133, and pro-migration factor SNAI1, as well as with downregulated antitumor mir7 RNA." (PMID 35327461, 2022). "(A) Overexpression of SATB2 with TETon (iSATB2) in normal human epidermal melanocytes (HEMA-LP) and in SKMEL2, SKMEL28, and A375 melanoma cells is sufficient to induce transcriptional activation of SOX10, SNAI1/2, PDGFB, and SEMA3F mRNA." (PMID 33527896, 2021).
melanoma (continued). "After 24-h GH treatment, SK-MEL-30 human melanoma cells showed a modest but significant increase of multiple EMT-related genes including mesenchymal markers ZEB-1, SNAI1, CLDN1 and SNAI2, while the epithelial marker CDH1 was significantly downregulated." (PMID 33291663, 2020). "NFATc2 showed a positive correlation with AXL, SNAI1, CDH2, and ZEB1 even in the TCGA melanoma dataset." (PMID 30710146, 2019). "The highest SNAI1 mRNA expression was observed in BRAF+ and BRAF− melanoma." (PMID 39273022, 2024). "The expression trend was similar and followed the immunohistochemistry results: the highest SNAI1 mRNA expression was observed in BRAF+ and BRAF– melanomas, supporting the role of SNAI1 as a potent epithelial repressor that cancer cells activate to detach from neighboring cells." (PMID 39273022, 2024). "Analysis of this model showed SNAI1 expression restricted to tdTomato-negative cells in the tumours indicating that Snail1 is reactivated in the melanoma microenvironment but not in the melanoma cells." (PMID 37516803, 2023). "A total of 195 TFs were predicted to be under the regulation of these elements including major, already established transcriptional dependency of melanoma (SOX10 and MITF) or factors like SNAI1 and SNAI2 that drive the transition toward the mesenchymal phenotype." (PMID 37408506, 2023). "First, we showed that JI130 and MEL56 inhibit cell migration in two invasive melanoma cell lines (MM029 and MM165) and downregulate the mRNA expression of the main EMT/invasion markers such as AXL, EGFR, MET, ZEB1, WNT5A, TGFβ, SNAI1, TWIST and MMPs." (PMID 37508519, 2023). "Analysis of the tumours confirmed SNAI1 expression in the recombined cells from the melanoma microenvironment that was absent in normal skin." (PMID 37516803, 2023). "We found that YY1-knockdown melanoma cells were more sensitive to TGF-β1 stimulation, in that YY1 knockdown cells treated with TGF-β1, boosted the expression of the EMT genes FN1, CDH2, ZEB1, SNAI1 and VIM, among others." (PMID 35693944, 2022). "However, in contrast to the “MITF-low” GES, melanoma cells with the “EMT” GES showed high expression levels of EMT-TFs (ZEB1, SNAI1, and PRRX1), which have been demonstrated to play a critical role in melanoma progression." (PMID 35884783, 2022). "In contrast, in melanoma cell lines, SNAI1 does not activate the transcription of ZEB1, thus, we have not included this interaction in our model." (PMID 32226439, 2020). "Importantly, among the TGF-beta target genes that were upregulated in our RNA-seq dataset are CD271, SNAI1, and JUNB, which are all known regulators of melanoma phenotype switching." (PMID 32123577, 2020). "Importantly, CD271, SNAI1, JUNB, and FOSB, the latter two as part of the AP-1 transcription factor complex, are all known regulators of melanoma phenotype switching." (PMID 32123577, 2020). "Though SNAI1/Snail and SNAI2/Slug are considered to play the same biological role in EMT triggering in epithelial tumors, it has been shown for melanoma cells that SNAI2/Slug is responsible for melanocytic differentiation and thus suppresses EMT." (PMID 31921836, 2019). "In the TCGA melanoma dataset, the top 312 genes with a positive correlation (down to Spearman r = 0.5) with the prototypic EMT marker ZEB1, were also positively correlated with SNAI1, NFATc2, CDH2, and AXL, but negatively with MITF and CDH1." (PMID 30710146, 2019). "Our study suggests that Snail (SNAI1) rather than Slug (SNAI2) plays a role during later stages of melanoma invasion and metastasis." (PMID 27172792, 2016). "On the other hand, enforced expression of TAF4 promoted expression of pluripotency- associated KLF4, OCT4 and NANOG, and NC-related MSX2, PAX7, SOX10 and SNAI1, reaffirming the critical role of hTAF4-TAFH activity in the maintaining of multipotency in melanoma cells." (PMID 27499390, 2016).
melanoma (continued). "To investigate whether this was also the case in melanoma, we used a similar approach and injected a VIVO-morpholino (VI-MO) that targets a splicing site in the Snai1 mRNA (Snail1-MO) into the tail vein of C57BL/6 mice with established BrafV600E-5555 lung metastases." (PMID 37516803, 2023). "Furthermore, MIST1 and SNAI1 transcription factors are thought to contribute to anoikis resistance by directly repressing PTEN, while knockdown of the NCAM adhesion molecule induced apoptosis in melanoma cells by suppressing Akt activation." (PMID 37181747, 2023). "We also noticed that transcriptional regulators of EMT including SNAI1, SNAI2, and RUNX2 were present in this list, supporting the hypothesis that the phenotypical plasticity gained through this transdifferentiation process concurs with melanoma aggressiveness." (PMID 37408506, 2023). "Moreover, the EMT transcription factors (EMT-TFs), such as ZEB (zinc finger E-box-binding homeobox) and SNAIL (zinc finger protein SNAI1), have even been shown to play an important role in tumor progression in non-carcinomas, such as melanoma and glioblastoma." (PMID 28640191, 2017).
colorectal cancer (92 papers, 2012 to 2026). A primary or metastatic malignant neoplasm that affects the colon or rectum. "The EMT-inducing TFs, Snai1, Slug, and Twist1, were upregulated in colorectal cancer (CRC)-associated tECs, both in primary tumors and in hepatic metastases when compared to paired nEC samples from adjacent tissue." (PMID 39095583, 2024). "Genome-wide chromatin association studies have revealed multiple genes to which SNAI1 binds in breast and colorectal cancer cells." (PMID 36171192, 2022). "Another member of the ECM+ prognostic triple, the SNAI1 transcription factor, was also linked to the poor prognosis of colorectal cancer." (PMID 34938324, 2021). "Finally, in tumor samples from colorectal cancer patients a direct association between stromal SNAI1 expression and the endothelial marker CD34 was observed." (PMID 30250018, 2018). "miR-145 antagonizes SNAI1-mediated stemness and radiation resistance in colorectal cancer, and reversed 5-fluorouracil (5-FU) drug resistance by directly targeting DNA damage-related gene RAD18 in colorectal cancer." (PMID 36077665, 2022). "SNAI1, upregulated in colorectal cancer specimens (1.3-fold and 4.5-fold increase), favors stem cell-like phenotype maintenance, while miR-145 acts as a CSCs’ suppressor." (PMID 36429127, 2022). "MAPKAPK5-AS1 regulates SNAI1 expression by sponging let-7f-1-3p and facilitates the progression of colorectal cancer." (PMID 35468721, 2022). "To uncover the regulatory role of NR1H2 and SNAI1 in colorectal cancer, we also performed DAVID functional enrichment analysis of the sets of their target genes inferred by miRGTF-net." (PMID 34938324, 2021). "For example, miR-145 confronted Snai1 and attenuated Snai1-mediated stemness and radiation resistance in colorectal cancer." (PMID 32195190, 2020). "Our data show that SNAI1 and Twist1 are already expressed in benign precursor lesions of colorectal cancer and that SNAI1 expression was significantly correlated with lower expression of CDH1." (PMID 23029563, 2012). "It has been shown that this miRNA is downregulated in colorectal cancer cell lines where endogenous SNAI1 was high (SW620: 800-fold and 15-fold downregulation when compared to HCT116 and SW40, respectively) and in SNAI1-overexpressing cell lines (DLD1—36% as compared to vector control)." (PMID 36429127, 2022). "Previous studies have pointed out that the high expression of Snai1 has a significant correlation with the metastasis, recurrence, and poor prognosis of a variety of epithelial-derived malignant tumors, including colorectal cancer, lung cancer, and breast cancer." (PMID 35434126, 2022). "Interestingly, re-annotation of the significantly enriched peaks obtained from SNAI1 ChIP-sequencing analysis in human colorectal cancer cells showed that SNAI1 occupies the proximal promoter region of FOXA1." (PMID 36171192, 2022). "A direct link between SNAI1 and FOXA1 is thus proposed based on reports from colorectal cancer where SNAI1 can directly repress the FOXA1 gene, and tumor cells acquire mesenchymal features upon FOXA1 knockout." (PMID 36171192, 2022). "Namely, SNAI1 regulates epithelial–mesenchymal transition (EMT) by suppressing E-cadherin and promotes chemoresistance in colorectal cancer." (PMID 34938324, 2021). "In conclusion, our data indicate that STAT-3 and NF-κB are involved in the M2-TAM-promoted EMT process of colorectal cancer cells and that PA and Cer decrease the mRNA expression of STAT-3, NF-κB, and SNAI1." (PMID 32222879, 2020). "miR-34a also have effect on colorectal cancer invasion and metastasis in conjunction with IL-6R, ZNF281, MET, snail family zinc finger 1 and 2 (SNAI1, SNAI2) and β-catenin (CTNNB1)." (PMID 30202241, 2018). "In our study EMT was detected in samples of colorectal cancer based on coordinated changes in the expression of the following genes: ZEB1, ZEB2, SNAI1, CDH1, and VIM." (PMID 25157365, 2014).
colorectal cancer (continued). "Also, in the colorectal cancer cell line HCT116, STAT3 knockdown resulted in higher Snail1 (Snail Family Transcriptional Repressor 1) expression and greater invasiveness than controls in cell invasion assays." (PMID 38339245, 2024). "At the molecular levels, this coincided with the downregulation of Nfkb1, Snai1 and Stat3 mRNA, in line with our previous study showing that PA and Cer were powerful inhibitors of an IL-10-STAT3-NF-κB signaling axis regulating EMT in colorectal cancer." (PMID 35457057, 2022). "We also included colorectal cancer EMT markers, TWIST1 and SNAI1." (PMID 34214079, 2021). "Previous studies on hepatocellular carcinoma, breast and colorectal cancers showed that sOPN could contribute to the metastasis through enhancing EMT-related transcription factors such as TWIST1, SNAI1 and SNAI2 and then decreasing the adhesion of tumor cells." (PMID 34070192, 2021). "Furthermore, SNAI1 regulates CSC activity and tumorigenicity in breast and colorectal carcinoma cells; and CRC patients with abundant SNAI1 expression exhibit high metastasis." (PMID 24565133, 2014). "We performed a quantitative RT-PCR assay to analyze the mRNA expression of SNAI1 (Snail1), TWIST1 (Twist1), CDH1 (E-cadherin) and CDH2 (N-cadherin) in FFPE tissue samples of colorectal adenomas (n = 41), colorectal cancer (n = 10) and normal colon mucosa (n = 10)." (PMID 23029563, 2012). "The result displayed that SNAI1 (Snail), a crucial EMT transcript factor, was one of the most relevant genes with H19, suggested H19 may involve in the progression of EMT in colorectal cancer." (PMID 32698890, 2020).
ovarian carcinoma (85 papers, 2009 to 2025). A malignant neoplasm originating from the surface ovarian epithelium. "DDR2 activates the AKT/SNAI1 pathway to enhance hexokinase activity, thereby modulating glycolysis in ovarian cancer cells." (PMID 40563472, 2025). "EMT’s transcription factor SNAI1 induced EMT in ovarian cancer cells (SKOV3 cells) and enhanced the invasiveness." (PMID 35523936, 2022). "First, a meta-analysis based on the TCGA database found that PD-L1 expression was closely correlated with MYC, SOX2, and SNAI1 in the endometrial and ovarian cancer data sets." (PMID 36582540, 2022). "In our study, low FTO expression increased the m6A modification of SNAI1 mRNA and promoted SNAI1 expression in ovarian cancer." (PMID 36358640, 2022). "In breast, pancreatic, and ovarian cancer cell lines the cell stemness in increased by SNAI1 overexpression and reduced by SNAI1 knockdown." (PMID 33806868, 2021). "By using two ovarian cancer cell lines expressing SNAI1, we demonstrate that SNAI1 represses other major EMT-TFs in epithelial (E) cell lines, whereas this regulatory pattern becomes more relaxed in an intermediate epithelial (IE) cell line." (PMID 32370157, 2020). "Using two ovarian cancer cell lines, we show that SNAI1 regulation on other core EMT-TFs switches from a repressive control in highly epithelial cells to an activation signaling in intermediate epithelial cells." (PMID 32370157, 2020). "In this study, we have reported the negative regulation of SNAI1 on SNAI2 expression in ovarian cancer via the recruitment of the histone deacetylase (HDAC) corepressor to the proximal E-box binding sites." (PMID 31165775, 2019). "Our meta-analysis demonstrated that PD-L1 is co-amplified along with MYC, SOX2, N-cadherin and SNAI1 in the TCGA endometrial and ovarian cancer datasets." (PMID 30283733, 2018). "The same group also profiled mesothelial clearance–competent and –incompetent ovarian cancer cell lines and concluded that mesenchymal genes, including SNAI1, ZEB1, and TWIST1 are enriched in the clearance-competent cells." (PMID 29861857, 2018). "This study is aimed to conduct a meta-analysis to evaluate the prognostic value of lymphovascular space invasion(LVSI) and to explore the potential association of SNAI1 and SNAI2 with LVSI in ovarian cancer." (PMID 28039463, 2017). "PITX2-induced TGF-β pathway regulated the expression of invasion-associated genes, SNAI1, CDH1 and MMP9 (p < 0.01) that accounted for enhanced motility/invasion of ovarian cancers." (PMID 26298390, 2015). "In ovarian cancer cells, SNAI1 primarily regulates intercellular and cell-matrix adhesion." (PMID 39980566, 2025). "Besides, SNAI1 induces the invasion, and metastasis of ovarian cancer, and is applied for the prediction and treatment of this cancer." (PMID 37017587, 2023). "To understand the early changes induced by SNAI1, we stably overexpressed full-length SNAI1 in two ovarian cancer cell lines: one belonging to the epithelial (E) phenotype (OVCA420) and the other belonging to the intermediate epithelial (IE) phenotype (OVCA429)." (PMID 32370157, 2020). "Moreover, our previous report on a panel of 43 ovarian cancer cell lines also showed that SNAI1 expression is enriched in cell lines with E and IE phenotypes, whereas expressions of TWIST1 and ZEB1/2 are higher in cell-line IM and M phenotypes." (PMID 32370157, 2020). "In ovarian cancer cells, miR-363-3p targets snail family transcriptional repressor 1 (SNAI1)." (PMID 31861937, 2019). "Similarly, promotion of EMT by hematopoietic PBX interacting protein, NANOG, TWIST1, SNAI1 FOXM1 accompanied acquisition of ovarian cancer cell resistance to conventional therapeutic agents, such as cisplatin, carboplatin or paclitaxel." (PMID 28792442, 2017). "Finally, we addressed whether the LPA-promoted signature associated with Hh (GLI1, BMI1) and EMT (SNAI1, TWIST1) genes has an impact on the clinical outcome of ovarian cancer patients." (PMID 34831435, 2021).